MIR6776 (microRNA 6776)
Synonyms: hsa-mir-6776
Gene: MicroRNA gene on chromosome 17 (2,692,861 to 2,692,919, reverse strand). Ensembl gene ENSG00000273606.
Homologues: Orthologues: chimpanzee MIR6776 (100% identical).